MMP3 (matrix metallopeptidase 3)
Diseases named in the same sentence as MMP3 in open-access papers (continued):
Sharing a sentence is not in itself a finding about the gene and the disease.
benign prostatic hyperplasia (4 papers, 2017 to 2020). A non-cancerous nodular enlargement of the prostate gland. "We conclude that tissue levels of MMP3 and MMP7 (finely regulated by their inhibitors TIMP1 and TIMP2) are altered in PCa compared to benign prostatic hyperplasia, which is of special relevance in elderly men." (PMID 28471417, 2017). "Levels of MMP-3 were assessed in patients with metastatic and non-metastatic prostate cancer, patients with benign prostate hyperplasia, and healthy males." (PMID 33371324, 2020).
chronic kidney disease (4 papers, 2019 to 2024). Impairment of the renal function secondary to chronic kidney damage persisting for three or more months. "As in other proinflammatory markers, the MMP-3 level can also be dependent on kidney function and may express a subclinical, low-grade inflammatory state which is present in chronic kidney disease patients." (PMID 33664330, 2021). "Furthermore, higher plasma MMP-3 was associated with higher plasma creatinine and lower eGFR, as has been reported earlier, and a recent study suggested that MMP-3 levels in serum could assist eGFR in the diagnosis of early chronic kidney disease." (PMID 39000435, 2024).
Cirrhosis (4 papers, 2022 to 2024). A chronic disorder of the liver in which liver tissue becomes scarred and is partially replaced by regenerative nodules and fibrotic tissue resulting in loss of liver function. "After erlotinib treatment, expression of antifibrotic pathways, including Mmp2, Mmp3, and Mmp8, were enhanced in PCLS from CDAHFD-induced cirrhosis, while expression of profibrotic pathways, including Mmp9 and Mmp13, were hampered." (PMID 39445861, 2024). "QuantSeq 3′ mRNA sequencing revealed thirty-three downregulated genes associated with ECM after the NK cell treatment of CCl4-induced cirrhosis, including six MMP genes (MMP3, MMP8, MMP9, MMP11, MMP12, and MMP14)." (PMID 37189708, 2023).
coronary aneurysm (4 papers, 2004 to 2020). Abnormal balloon- or sac-like dilatation in the wall of coronary vessels. "The results showed that the MMP-3 5A allele was associated with the occurrence of coronary aneurysm." (PMID 32982940, 2020). "In our study, it appears that elevated MMP-3 activity may represent a risk factor for coronary aneurysm formation." (PMID 15482602, 2004). "High levels of MMP-3 have also been reported in the blood serum of patients with coronary arteries aneurysm." (PMID 19886986, 2009). "MMP-3 may play role in the pathogenesis of coronary aneurysm development through increased proteolysis of extracellular matrix proteins." (PMID 15482602, 2004). "Because elevated MMP-3 levels likely contribute to the development of coronary aneurysms, this matrix-degrading enzyme may represent an important therapeutic target." (PMID 15482602, 2004). "We conclude that MMP-3 overexpression due to a proteolytic imbalance may lead to coronary aneurysm development through degradation of matrix components, especially lamina elastica." (PMID 15482602, 2004). "Finally, the recent observation that high circulating levels of MMP-3 are associated with coronary lesions in Kawasaki disease also supports an important role for MMP-3 in the pathogenesis of coronary aneurysms." (PMID 15482602, 2004). "MMP3, on the other hand, is highly expressed in human AAA and a common SNP in the promoter region of the MMP3 gene was found to correlate positively with AAA formation and coronary aneurysms in humans." (PMID 28116311, 2017).
Crohn disease (4 papers, 2023). A gastrointestinal disorder characterized by chronic inflammation involving all layers of the intestinal wall, noncaseating granulomas affecting the intestinal wall and regional lymph nodes, and transmural fibrosis. "Also in the case of pediatric patients diagnosed with Crohn’s disease, the concentration of MMP-3 and MMP-9 increases with the activity of the disease." (PMID 37895400, 2023). "The most frequently analyzed metalloproteinases in Crohn’s disease are: MMP-1, MMP-3, MMP-7, MMP-8 and MMP-9." (PMID 37895443, 2023). "They assessed the concentration of MMP-3 and MMP-9 in Crohn’s disease." (PMID 38203373, 2023). "MMP-3 and MMP-10 are the main enzymes indicating the development of Crohn’s disease." (PMID 37895400, 2023). "MMP-1, MMP-3, MMP-7, MMP-8 and MMP-9 are biomarkers of Crohn’s disease." (PMID 37895400, 2023).
endometrial cancer (4 papers, 2019 to 2025). Primary or metastatic malignant neoplasm involving the endometrium (mucous membrane that lines the endometrial cavity). "We investigated the levels of MMP-7, MMP-26, MMP-3, and MMP-10 in comparison with the levels of a tumor marker (CA125) in the plasma of postmenopausal patients in early stages of endometrial cancer (EC) compared with control groups: patients with benign lesions (myoma uteri) and healthy controls." (PMID 40332487, 2025).
esophageal squamous cell carcinoma (4 papers, 2020 to 2023). Esophageal squamous cell carcinoma (ESCC) is a type of esophageal carcinoma (EC) that can affect any part of the esophagus, but is usually located in the upper or middle third. "For example, NSUN2 promotes tumor metastasis and cisplatin resistance by methylating NMR (also known as LINC01672) ncRNA, which in turn recruits BPTF and promotes the expression of matrix metalloproteinase 3 (MMP3) and MMP10 in esophageal squamous cell carcinoma." (PMID 37612540, 2023). "In esophageal squamous cell carcinoma (ESCC), lncRNA NMR methylated by NSUN2 combines with the chromatin regulator BPTF to promote the expression of MMP3 and MMP10 via the ERK1/2 pathway; thus, promoting the progression of ESCC." (PMID 34777473, 2021).
gastric ulcer (4 papers, 2010 to 2025). An ulcerated lesion in the mucosal surface of the stomach. "We proposed that inflammatory cells of gastric ulcers participate vigorously in the healing process and upregulate MMP-3 and TIMP-1 strongly either in H. pylori infection or in the other two NSAID-use groups with or without H. pylori infection." (PMID 22645431, 2012). "pylori-infected patients enrolled, 470 patients (265 with gastritis, 118 with duodenal ulcer, and 87 with gastric ulcer) received SNPs analysis of MMP-3-1612 6A > 5A, MMP-7-181 A > G, MMP-9exon 6 A > G, TIMP-1372 T > C and TIMP-2-418 G > C by PCR-RFLP." (PMID 20707923, 2010). "This study demonstrates that MMP-3, -7 and -9 and TIMP-1 may play a potential role in gastric ulcer formation or the healing process." (PMID 22645431, 2012). "By comparing gastric ulcer and nonulcer tissues within the same individual, this study is highly original in revealing how MMP-3, -7, and -9 and TIMP-1 expressions are upregulated in gastric ulcers induced by H. pylori infection and NSAID use, respectively (P < 0.05)." (PMID 22645431, 2012). "Over inflammatory cells of the gastric ulcer lamina propria, only MMP-9 expression (not MMP-3 and TIMP-1) was significantly higher in the H. pylori-infected group than in the other two NSAID-use groups with or without H. pylori infection (P < 0.001)." (PMID 22645431, 2012). "MMP-3, MMP-9, and TIMP-1 expressions over inflammatory cells of the gastric ulcer lamina propria were also higher than in nonulcer tissues (P < 0.001)." (PMID 22645431, 2012).
gastritis (4 papers, 2010 to 2024). Inflammation of the stomach. "H. pylori eradication with antibiotics and a treatment with proton-pump inhibitor led to the decrease of the cytokines (in all groups) and MMP-3 amount in tissue specimens from gastritis patients." (PMID 35163805, 2022). "We demonstrated that the culture supernatant of CD4+T cell from H. pylori-positive gastritis patients promoted MMP3 and MMP9 secretion of GES-1 cells." (PMID 34589088, 2021). "Of H. pylori-infected patients, the MMP-3 6A6A genotype were more common in patients with duodenal ulcers than in those with gastritis (87.7% vs. 74.9%, p < 0.05) in females." (PMID 20707923, 2010). "There was a higher rate of MMP-3 6A6A genotype in patients with duodenal ulcers than in patients with gastritis (87.7% vs. 74.9%, p < 0.05)." (PMID 20707923, 2010). "Serum levels of MMP-9 (but not MMP-3 and MMP-7) were also higher in patients with H. pylori–associated gastric ulcer in comparison to those of patients with H. pylori–positive gastritis and cancer." (PMID 35163805, 2022).
Hyperglycemia (4 papers, 2021 to 2025). An increased concentration of glucose in the blood. "Having established β-cell dysfunction under hyperglycemia, we next examined how this stress affects MMP-3 gene expression." (PMID 41141358, 2025). "Together, the qPCR data supports a role for cytokine treatment and hyperglycemia in mediating the upregulation of MMP-3 in mouse and human islets." (PMID 41141358, 2025). "Treatment with proinflammatory cytokines or hyperglycemia increased MMP-3 gene expression and protein levels in mouse and human islets." (PMID 41141358, 2025). "We suspect this discrepancy is due to MMP-3 being a secreted matrix metalloproteinase, and thus MMP-3 was likely released into the media in response to cytokine stress or hyperglycemia." (PMID 41141358, 2025). "By contrast, the effects of PA on the mRNA expression of gene encoding type 2 collagen and MMP-3 did not change under hyperglycemia." (PMID 38339087, 2024). "For example, hyperglycemia fosters tumor cell growth by creating a nutrient‐rich environment and by promoting the resistance of PC cells to gemcitabine through the regulation of the ROS/MMP‐3 signaling pathway." (PMID 38523554, 2024). "Hyperglycemia has been shown to increase the activity of matrix metalloproteinase (MMP)-9 and MMP-3 in the ischemic region, exacerbate blood-brain barrier dysfunction and hemorrhagic transformation after recanalization." (PMID 35126278, 2021). "In the NOD mouse model of T1D, MMP-3 expression progressively increased from normoglycemia to hyperglycemia, independent of insulitis score." (PMID 41141358, 2025). "In NOD pancreas sections, increased MMP-3 expression in β-cells correlates with loss of COL IV during insulitis and hyperglycemia; however, this was independent of insulitis score." (PMID 41141358, 2025). "However, in hyperglycemic NOD mice, COL IV degradation was more extensive and MMP-3 expression was greater than in age-matched normoglycemic counterparts, again independent of insulitis score, implying that hyperglycemia alone may be sufficient to induce ECM degradation by the β-cell." (PMID 41141358, 2025).
invasive breast carcinoma (4 papers, 2018 to 2025). A carcinoma that infiltrates the breast parenchyma. "Aberrant MMP3 expression promotes epithelial malignancy, is elevated in invasive breast cancer, and is associated with poor prognosis." (PMID 41462902, 2025). "It has been reported that higher levels of MMP3 is viewed as a marker of unfavorable prognosis in invasive breast cancer." (PMID 30237863, 2018). "DMC and BDMC, however, may exhibit cell-specific effects as treatment selectively up-regulated MMP-3 expression in MDA-MB-231 invasive breast carcinoma cells but not in MCF-7 non-invasive breast cancer cells." (PMID 31295798, 2019).
lung adenocarcinoma (4 papers, 2015 to 2025). A carcinoma that arises from the lung and is characterized by the presence of malignant glandular epithelial cells. "In lung adenocarcinoma, high expression of CCL20, IL23A, MMP1 and MMP3 was significantly associated with poor patient prognosis, whereas high expression of FOS, HLA-DPA1, HLA-DPB1, HLA-DQA1, HLA-DQB1 and HLA-DRA was significantly associated with improved patient prognosis." (PMID 40016789, 2025). "In the second comparison, a classification tree which sequentially included the proteins CA19-9, CA15-3, MMP-3, and kallikrein-12 yielded a sensitivity of 83% (95% CI 64.2–94.2%) and a specificity of 89.7% (95% CI 73–98%) for separating 29 lung adenocarcinomas from 29 mesotheliomas." (PMID 26962828, 2016). "Overall we conclude that MMP3 is prognostic for poor survival in lung adenocarcinoma, with particularly strong association with outcome in nonsmokers." (PMID 26807201, 2015). "In order to further investigate the mechanism of inhibition of lung adenocarcinoma by WFEA, qRT-PCR and Western blot was carried out to detect the expression levels of PI3K-AKT signaling pathway related molecules (AKT, PI3K, MMP3, Caspase3 and Bcl-2)." (PMID 36949111, 2023). "Similarly, 20 lung adenocarcinomas and 20 mesotheliomas were tested for the expression of the pleural fluid proteins CA19-9, CA15-3, kallikrein-12, and MMP-3." (PMID 26962828, 2016).
lymph node metastasis (4 papers, 2016 to 2023). "In our analysis, a high expression of MMP-3 was associated with elevated CEA levels, more lymph node metastases, and more advanced disease stages, and the MMP-3 expression level was associated with long-term prognosis, such as five-year DFS." (PMID 37511338, 2023). "MMP-1 expression in EC cells is associated with poor prognosis; MMP-2 and MMP-3 expression is positively correlated with depth of invasion, lymph node metastasis, and vessel permeation." (PMID 26916665, 2016). "The high-APRIL/TNFSH13-expression group showed a significantly higher rate of metastatic lesions than the low-expression group, whereas the high-MMP-3-expression group had higher CEA levels, more lymph node metastases, and more advanced disease stages than the low-expression group." (PMID 37511338, 2023). "The concentrations of MMP3 were not obviously correlated with any clinicopathological parameters including age, tumor size, T classification, lymph node metastasis, distant metastasis and clinical stage, but significant association was found with gender (P < 0.001)." (PMID 32922541, 2020).
nasopharyngeal carcinoma (4 papers, 2015 to 2022). A carcinoma arising from the nasopharyngeal epithelium. "MMP-3, MMP-10 and MMP-12 have been shown to be up-regulated in hnRNP-K-overexpressing lung and nasopharyngeal cancer cells." (PMID 26713736, 2015).
oral squamous cell carcinoma (4 papers, 2007 to 2023). "In Colo357 cells expressing PDX1, there is an increase in MMP3 gene expression, and high expression levels in oral squamous cell carcinoma cells are associated with metastasis and poor prognosis for patients." (PMID 34503200, 2021). "This study examines the association of single nucleotide polymorphisms in promoter regions of MMP-1 and MMP-3 with susceptibility to oral squamous cell carcinoma (OSCC)." (PMID 17919326, 2007). "Overexpression of common genes associated with tobacco-induced oral squamous cell carcinoma (OSCC), such as MMP1, MMP3, MMP9, YAP1, CYP1A1, and CYP1B1, was also observed." (PMID 36835505, 2023).
rotator cuff tear (4 papers, 2019 to 2025). "Promoter polymorphisms in MMP-3 have been associated with increased rotator cuff tear susceptibility, underscoring a genetic contribution to MMP-mediated tendon integrity." (PMID 40688916, 2025). "Another study concluded that genetic polymorphisms in MMP-1 and MMP-3 were associated with rotator cuff tears." (PMID 36833294, 2023). "Together, these findings indicate that, following rotator cuff tear, an early TNF-α-driven increase in NTN4 may serve as a key intermediary that prolongs MMP-3-mediated matrix degradation, thereby linking acute inflammation to sustained tendon remodeling." (PMID 40688916, 2025).
systemic sclerosis (4 papers, 2010 to 2025). A chronic disorder, possibly autoimmune, marked by excessive production of collagen which results in hardening and thickening of body tissues. "The authors indicated that higher concentrations of TIMPs in patients with systemic sclerosis as compared with healthy controls were associated with the inhibition of MMP-3 production." (PMID 33371324, 2020). "Therefore, it cannot be ruled out that the increase of TGF-β concentration in the blood plasma of patients with systemic sclerosis demonstrated, in this study, may be the cause of changes in the activity of other MMPs, including MMP-3." (PMID 32382564, 2020). "Among other factors, which may also regulate the concentration of MMP-3 in the blood of patients with systemic sclerosis, transforming growth factor β plays a significant role." (PMID 32382564, 2020).
triple-negative breast carcinoma (4 papers, 2019 to 2024). An invasive breast carcinoma which is negative for expression of estrogen receptor (ER), progesterone receptor (PR), and human epidermal growth factor receptor 2 (HER2). "On the other hand, zerumbone has been shown to prevent IL-1β-induced invasion of triple-negative breast cancer cells by inhibiting the expression of IL-8 and matrix metallopeptidase 3 (MMP3)." (PMID 39769450, 2024). "The MT3 gene, one of the genes affected by cobalt boride exposure, was claimed to have proliferative, cell cycle, and apoptotic effects on cancer cells by regulating the expression of MMP3 in the triple-negative breast cancer (TNBC) cell line." (PMID 36500178, 2022).
acute kidney injury (3 papers, 2021 to 2024). Sudden and sustained deterioration of the kidney function characterized by decreased glomerular filtration rate, increased serum creatinine or oliguria. "Since elevated MMP-3 levels may be associated with renal failure, caution should be exercised when interpreting its elevation in AAV patients with renal dysfunction." (PMID 39702436, 2024). "MMP3 could mediate shedding of kidney injury molecule-1 in renal tubular epithelial cells during acute kidney injury." (PMID 37006258, 2023).
acute respiratory distress syndrome (3 papers, 2022 to 2025). Progressive and life-threatening pulmonary distress in the absence of an underlying pulmonary condition, usually following major trauma or surgery. "Moreover, inhibiting MMP-3 is emerging as a promising therapeutic approach for conditions such as COVID-19-associated acute respiratory distress syndrome (ARDS), reflecting functions that extend beyond extracellular proteolysis to include the modulation of immune responses." (PMID 40277922, 2025).
anaplastic thyroid cancer (3 papers, 2020 to 2025). "MMP3 is also associated with anaplastic thyroid cancer (ATC) cell invasion and migration, suggesting it may be developed as a novel therapeutic target for ATC." (PMID 40575254, 2025).
Anxiety (3 papers, 2016 to 2026). Intense feelings of nervousness, tension, or panic often arise in response to interpersonal stresses. "Subjects in cluster B (older, sinonasal disease) have the highest median age, more symptoms of anxiety and depression (highest median HAD score, 12-27), more nasal symptoms (highest Sino-Nasal Outcome Test 20 score), and high levels of serum periostin and sputum MMP3." (PMID 26851968, 2016).